CCL2 (C-C motif chemokine ligand 2)
Diseases named in the same sentence as CCL2 in open-access papers (continued):
Sharing a sentence is not in itself a finding about the gene and the disease.
breast cancer (continued). "Ca-TAT delivery of huCCL2si1 or huCCL2si2 efficiently transfected MDA-MB-231 breast cancer cells embedded in collagen and silenced CCL2 expression at 24 and 48 hours." (PMID 27283985, 2016). "Recent studies demonstrate that CCL2 also signal to breast cancer cells to regulate survival and invasion." (PMID 27283985, 2016). "Recent studies have shown that CCL2 enhances cancer stem cell renewal of some luminal breast cancer cell lines in vitro." (PMID 27283985, 2016). "Here we report that CCL2 promotes mammary carcinoma development in a clinically relevant murine model of breast cancer." (PMID 27820834, 2016). "CCL2 has been shown to recruit inflammatory monocytes facilitating the breast cancer metastasis, and disinhibition of CCL2 accelerates the breast cancer metastasis." (PMID 27391090, 2016). "LPS stimulation has been shown to induce promotion of macrophage activation, phagocytosis, and CCL2 secretion by 4T1 cells, indicating an enhanced macrophage-mediated inflammation in breast cancer cells." (PMID 27983683, 2016). "For example, CCL2 concentrations in human breast cancers are higher than in normal breast tissue and serum CCL2 is higher in breast cancer patients than in healthy controls." (PMID 27820834, 2016). "Ca-TAT/siRNA complexes penetrated 3D collagen cultures of breast cancer cells and inhibited CCL2 expression more effectively than conventional antibody neutralization." (PMID 27283985, 2016). "Targeted disruption of Ccl2 slowed the growth of activated Her2/neu-driven mammary tumors and prolonged host survival." (PMID 27820834, 2016). "Through p42/44 MAPK, CCL2 enhances the survival and invasiveness of endometrial stromal cells and coordinates the survival and motility of breast cancer cells." (PMID 27458015, 2016). "In summary, these studies indicate that Ca-TAT/siRNA complexes efficiently knock down CCL2 expression in breast cancer cells." (PMID 27283985, 2016). "A study, using a global gene expression analysis approach, identified chemokine (C-C motif) ligand 2 (CCL2) as the transcript most effected by silencing FXYD5 in MDA-MB-231 breast cancer cells." (PMID 27066483, 2016). "Ca-TAT/siRNA complexes were observed to efficiently transfect MDA-MB-231 and DCIS.com breast cancer cells plated in 2D and 3D cultures, and reduce CCL2 expression more effectively than CCL2 neutralizing antibodies." (PMID 27283985, 2016). "Further corroborating our findings, we found that mRNAs for CXCL16 as well as for IL8, CSF2, MMP9, EDN1 and CCL2 all were expressed at significantly higher levels in basal-like breast cancers as compared with luminal A tumours." (PMID 27725631, 2016). "Elevated CCL2 levels also inversely correlated with relapse-free survival, and predicted advanced tumor stage and lymph node involvement in breast cancer patients." (PMID 26885690, 2016). "For example, the expression of CCL2 which is predominantely involved in breast cancer progression, was reduced in the CD44+/β1+ sub-population compared to Non- CD44+/β1+ cells (Data not shown)." (PMID 27835603, 2016). "These include chemokine C-C motif ligand 2 (CCL2), also known as macrophage chemoattractant protein 1 (MCP-1), which has been implicated in carcinogenesis and metastasis, including in CRC and breast cancer." (PMID 27058904, 2016). "Here, we used a mouse model of breast cancer in which the MMTV LTR drives activated HER2/neu (MMTV-neu) to investigate how CCL2 and CCR2 affect tumor development." (PMID 27820834, 2016). "Taken together, these data indicate that CCL2 gene silencing inhibits self-renewal of MDA-MB-231and DCIS.com breast cancer cells." (PMID 27283985, 2016). "Recently, there are several researches in Hela cells, breast cancer, colon carcinoma and melanoma showing CCL2/CCR2 axis is related to the activation of MAPK pathways in ERK1/2, p38, and JNK." (PMID 26701209, 2016). "In breast tumor bearing mice, continuous treatment with CCL2 neutralizing antibodies inhibited mammary tumor progression." (PMID 27283985, 2016).
breast cancer (continued). "This suggests that CCL2 is required both for the development of EPCs and for their mobilization by mammary cancers." (PMID 27820834, 2016). "Recently, however, one remarkable study published on Nature alerted that, cessation of CCL2 inhibition would accelerate breast cancer metastasis in mice." (PMID 26701209, 2016). "The chemokine CCL2 is overexpressed in invasive breast cancers, and regulates breast cancer progression through multiple mechanisms." (PMID 27283985, 2016). "Our results are also consistent with other mouse models in which CCL2 attracts tumor-promoting macrophages to metastatic sites of mammary carcinomas driven by polyoma middle T antigen." (PMID 27820834, 2016). "In particular, MyD88 is required for nerve injury induced upregulation of CCL2, in DRG neurons, consistent with another report in which the release of CCL2 was dependent on MyD88 pathway in murine mammary carcinomas cells." (PMID 27312666, 2016). "To test the effect of CCL2 on the behavior of HER2/neu-driven mammary carcinomas, we compared the overall survival of mice carrying the MMTV-neu transgene and a targeted deletion of Ccl2 (neu+Ccl2-/-) to mice carrying the MMTV-neu transgene alone (neu+)." (PMID 27820834, 2016). "Bonapace and colleagues’ article demonstrates mammary tumour secretion of CCL2, enabling recruitment of inflammatory monocytes to the primary tumour and the metastatic site." (PMID 25990313, 2015). "CCL2 expression in tumors is correlated with higher histological grade breast cancer and is a significant indicator of early relapse." (PMID 25599228, 2015). "Macrophage infiltration and CCL2 expression are correlated with poor prognosis and metastasis in human breast cancer." (PMID 26424146, 2015). "Among those identified chemokines, CCL2 has long been recognized as a regulator of TAMs in different human cancers, such as breast cancer and colon cancer." (PMID 26155942, 2015). "During the M1-to-M2 transition of macrophages the molecular changes occurring can have profound effect on breast cancer cell behaviour; notably, the levels of the cytokines CSF-1 and CCL2 are elevated during this transition." (PMID 26174804, 2015). "We showed that a main macrophage chemoattractant, chemokine CCL2, is produced in elevated amounts by the E0771 mammary tumor cells, which is enhanced by the crosstalk between adipocytes from obese adipose tissues with E0771 cells and macrophages." (PMID 25599228, 2015). "It has been reported that high levels of CCL2 in breast cancer specimens correlate with high number of macrophages in the primary tumors, suggesting pivotal roles of CCL2 in macrophage recruitment to the tumor microenvironment." (PMID 26275794, 2015). "In tumor-bearing mice, CC chemokine ligand 2 (CCL2) neutralizing antibodies inhibit the growth and liver metastases of primary breast cancer by reducing cell proliferation, survival, and tumor-associated macrophage (TAM) recruitment." (PMID 25885919, 2015). "Studies have also proposed CCL2 as a poor prognostic marker in multiple different tumour types, in particular breast cancer." (PMID 26358505, 2015). "We recently demonstrated that anti-CCL2 antibody treatment decreases the number of MAMs at the metastatic sites and reduces metastatic tumor burden in an experimental model of breast cancer lung metastasis." (PMID 26275794, 2015). "CCL2 production, by the tumor and/or cells within the stromal microenvironment, recruits Gr-1+ cells to breast cancer lung metastases and leads to the subsequent recruitment of metastasis-associated macrophages." (PMID 25882816, 2015). "Our results show that among the three cell types studied individually, E0771 mammary tumor cells are by far the main producers of CCL2, compared to macrophages and adipocytes." (PMID 25599228, 2015). "VEGF-A and CCL2 expression were also significantly reduced in response to CoREST1 knockdown in another basal-type breast cancer cell line, SUM159." (PMID 25793264, 2015).
breast cancer (continued). "Surprisingly, C57BL/6 BMDMs cultured with 4T1 mouse mammary carcinoma-conditioned medium exhibited a 2–3 fold increase in the production of TNFα, IL-6, and CCL2 in the presence of LPS." (PMID 26177198, 2015). "Overall, our results demonstrate the extent to which canine mammary carcinoma cells influence the macrophage phenotype and the relevance of a feedback loop between these cells, involving CSF-1 and CCL2 as important mediators." (PMID 26174804, 2015). "We observed that BMDM conditioned with 4T1 murine mammary carcinoma culture medium displayed an increased production of monocyte chemoattractant CCL2 and promoted macrophage chemotaxis, which was in concordance with other studies." (PMID 26177198, 2015). "In particular, the aberrant production of IL-6 and CCL2 in mammary cancer activates STAT3 in CAFs, which finally sustains tumor-associated inflammation and is required for breast cancer cell migration." (PMID 25136593, 2014). "Cancer-associated fibroblasts (CAFs) and fibroblasts that are activated by coculture with cancer cells secrete high levels of CCL2, which affects the sphere-forming phenotype (stem cell-specific) of breast cancer cells and CSC self-renewal." (PMID 25165728, 2014). "We also found a marginal increase in the levels of secretion of CCL2, which has been shown to stimulate the migration of breast cancer cells." (PMID 25344915, 2014). "CCL2 is a chemokine that has been heavily investigated in prostate, ovarian and breast cancers because CCL2 regulates the recruitment of monocytes and macrophages to tumors and other sites of inflammation." (PMID 26932379, 2014). "Co-culturing also lead to changes in gene expression in the breast cancer cells, which upregulated a shared receptor for CCL2 and CCL7, the chemokine receptor CCR1 upon co-culturing with tumor-supportive fibroblasts." (PMID 24068959, 2013). "IL-1β, a potent activator of NF-κB signaling, produced an upregulation in chemokines CCL-2, -7, -8 similar to that seen by co-culture with breast cancer cells." (PMID 24068959, 2013). "It is evident that CCL2 (MCP-1), CCL5 (RANTES), and CXCL8 (IL-8) have pro-malignant activity that is associated with breast cancer progression and more advanced disease." (PMID 24260134, 2013). "The results of our study indicate that significant associations exist between CCL2 & CCL5 and TNFα & IL-1β in breast cancer, along different stages of disease course." (PMID 21486440, 2011). "We provide evidence to a coordinated expression of the inflammatory chemokines CCL2 & CCL5 and the inflammatory cytokines TNFα & IL-1β in breast cancer, all having causative roles as tumor-promoting factors in this disease." (PMID 21486440, 2011). "In this study, we asked if associations exist between the inflammatory chemokines CCL2 & CCL5 and the inflammatory cytokines TNFα & IL-1β in breast cancer." (PMID 21486440, 2011). "Recently, much attention has been given to the roles of inflammatory chemokines and cytokines in breast cancer, with emphasis on the chemokines CCL2 and CCL5, and the cytokines tumor necrosis factor α (TNFα) and interleukin 1β (IL-1β)." (PMID 21486440, 2011). "Therapeutic strategies targeting TAMs in breast cancer have evolved from depletion approaches (CSF1/CSF1R blockade) to inhibition of monocyte recruitment (CCL2/CCR2 axis), functional reprogramming (CD40 agonism, PI3Kγ inhibition), and macrophage-directed checkpoint modulation (CD47-SIRPα axis)." (PMID 42122206, 2026). "Therefore, the therapeutic impact of nAb‐CCL2 is expected to be particularly beneficial for patients with breast cancer who are obese." (PMID 41160815, 2026). "We analyzed the expressions of the FA/HIF‐1α/CCL2 axis in breast cancer tissues from patients." (PMID 41160815, 2026). "Due to the small sample sizes for basal-like (n = 10) and HER2+ breast cancers (n = 7), we did not analyze associations between CCL2 and HGF in these subtypes." (PMID 40736024, 2025).
breast cancer (continued). "As CCL2, HGF and CCL2/HGF treatment of breast cancer cells led to differences in glucose metabolism, we examined for expression of glycolytic proteins over time, including glucose transporter 1 (GLUT1) and rate limiting enzymes HK2, lactate dehydrogenase (LDHA) and pyruvate kinase M (PKM)." (PMID 40736024, 2025). "However, most patients exhibited a reduction in plasma CCL2 levels after curative surgery, suggesting that individuals with breast cancer tended to exhibit higher plasma CCL2 levels." (PMID 39749673, 2025). "Moreover, CAFs also secrete elevated levels of chemokine C-C motif ligand 2 (CCL2) to induce the NOTCH1 pathway in breast cancer cells, thereby maintaining their stemness." (PMID 40296919, 2025). "TAMs releasing CCL2 is correlated with worse prognosis in breast cancer." (PMID 39981232, 2025). "How might interactions between breast cancer cells with the microenvironment regulate CCL2/CCR2 and HGF/MET signaling?" (PMID 40736024, 2025). "In summary, our data delineate a novel immunological mechanism through which γδ T cells recruited to the TME of HR+HER2− mammary tumors upon CCL2 secretion as driven by CDK4/6 inhibitors promote the IL17-dependent repolarization of TAMs toward a CX3CR1+ profile associated with resistance to therapy." (PMID 40662849, 2025). "Similarly, in the xenograft mice models of breast cancer, the silencing of the CCL2 gene resulted in reduced tumor growth and metastasis." (PMID 41463161, 2025). "Propagermanium, a CCL2 inhibitor, has shown promising results, downregulating serum IL‐6 levels in a phase I clinical trial, as well as demonstrating clinical safety and holding potential as an antimetastatic agent in breast cancer treatment." (PMID 39749673, 2025). "The regulatory mechanisms of CAA in breast cancer are complex, including inflammatory adipokine secretions such as IL-1β, CCL2, TNFα, CCL5, and leptin, as well as IL-6 metabolic reprogramming by altering the metabolism of macronutrients and remodeling of the extracellular matrix." (PMID 39858015, 2025). "Previously, it has been demonstrated that in MCF7 breast cancer cells, STAT3 collaborates with FRA1 and c-JUN AP1 components to activate the MMP9 promoter, while in HepG2 hepatoma cells, STAT3 associates with HDAC1 to inhibit IL6-induced CCL2 transcription." (PMID 39274912, 2024). "Moreover, CCL2 SNPs were more likely to be associated with PR-positive breast cancer, while CXCL12 SNPs were associated with three main subtypes of breast cancer." (PMID 39703847, 2024). "Importantly, tumor cell-derived and lung stroma-derived CCL2 was critical for the monocytes to mediate mammary tumor metastasis, validated by systemic blocking of CCL2 and by CCL2 gene knockout in the tumor cells." (PMID 38786066, 2024). "CCL2 expression in breast cancer stroma may also contribute to the overall levels of CCL2 levels observed in tissues and in serum." (PMID 38973385, 2024). "CCL2 is a pro-tumorigenic cytokine that attracts TAMs and stimulates metastasis in breast cancer." (PMID 39623404, 2024). "Interestingly, CCL2 was reported to be a target gene of the canonical Wnt pathway in breast cancer, and the interaction between β-Catenin and CCL2 is thought to promote monocyte migration toward glioblastoma cells." (PMID 38622714, 2024). "Inhibition of CCL2 depletes inflammatory monocytes and macrophages, reducing tumor growth and dissemination in different experimental models, such as prostate cancer, melanoma, breast cancer, lung cancer, and liver cancer." (PMID 38769475, 2024). "M2 TAM derived CCL2 promoted in turn breast cancer cell stem cell properties." (PMID 39044824, 2024). "In addition, TAM production of IL-1β, induced by CCL2, resulted in systemic inflammatory cascades leading to the neutrophil-mediated promotion of mammary tumor metastasis in mice." (PMID 39003350, 2024).
breast cancer (continued). "Concerningly, interruption of CCL2 inhibition in several metastatic mouse models of breast cancer models appears to accelerate bone marrow monocyte release and increase the rates of metastasis and death, suggesting that caution should be exercised with CCL2/CCR2 inhibitor development." (PMID 39588367, 2024). "However, it is noteworthy that discontinuation of anti-CCL-2 therapy can lead to rebound, increasing the liberation of monocytes formerly lodged inside the bone marrow, and thus expediting breast cancer metastasis through the promotion of angiogenesis." (PMID 39065562, 2024). "In the same report, CCL2-mediated monocyte recruitment to the lung premetastatic niche was also critical for spontaneous metastasis of orthotopically injected MDA-MB-231 human breast cancer cells." (PMID 38786066, 2024). "Association of CCL2 and CXCL12 gene SNPs with Breast Cancer subtypes." (PMID 39703847, 2024). "Studies had shown that S100A14 might be related to the breast cancer metastasis by promoting expression of chemokines CCL2 and CXCL546." (PMID 38762700, 2024). "Association of CCL2 and CXCL12 gene SNPs with breast cancer susceptibility." (PMID 39703847, 2024). "In this study, we examined whether eight single nucleotide polymorphisms (SNPs) of CCL2 and CXCL12 influenced the susceptibility to breast cancer and analyzed their relationships with different subtypes of breast cancer." (PMID 39703847, 2024). "However, the interruption of CCL2 inhibition has shown to promote a rebound of pro-tumour myeloid cells inducing mouse breast cancer metastasis." (PMID 36161514, 2023). "Silencing CCL2 expression by TAT cell-penetrating peptides noncovalently cross-linked to siRNAs (Ca-TAT/siRNA) significantly reduced CCL2 expression in PyMT mammary tumors and decreased cell proliferation and survival." (PMID 37208442, 2023). "Based on these results, we suggest that pan-HER inhibitors, such as neratinib, could be more effective than TRZ in modulating CCL2 levels in breast cancer with EGFR and HER2 co-expression." (PMID 36674955, 2023). "CCL2 could induce the production of IL-1β in TAMs and lead to neutrophil expansion and systemic inflammation-mediated metastasis in breast cancer." (PMID 36674955, 2023). "IL-6, IL-8 and CCL-2 cytokines are mediators of tumour invasion and metastasis, and their increased levels are associated with cancer stem cell (CSC) enrichment and greater tumour stage and grade in breast cancer." (PMID 36674737, 2023). "Moreover, CCL2 release from mammary tumours attracts the CCR2-expressing monocytes produced by bone marrow." (PMID 37680708, 2023). "However, the mechanism that induces CCL2 expression in breast cancer with EGFR and HER2 co-expression remains to be further explored." (PMID 36674955, 2023). "For example, CCL2 secreted by TAMs increases chemoresistance in breast cancer cells." (PMID 36766725, 2023). "Upon investigating the mammary tumor tissue from docetaxel-treated mice, we found an increase in protumor immune infiltrates including M2 macrophages, MDSCs, Tregs, γδT cells, and an enriched gene signature comprising Vim, Spp1, S100a6, Ccl2, and Lgals1 genes." (PMID 37699010, 2023). "Further, CCL2 production has been shown to be regulated by TGF-β during breast cancer progression." (PMID 37468567, 2023). "Furthermore, CD163+macrophages were found to be located around adipocytes in breast cancer tissues, and their recruitment and polarization were mediated by the upregulated expression of CCL2 and CCL5 in the TAME." (PMID 37454080, 2023). "The aggregation of 27-HC stimulates the proliferation of estrogen receptor-positive breast cancer cells, promotes the expression of various chemokines such as CCL2 and CCL3 by TAMs and recruits monocytes to the primary tumor site, which in turn promotes the development of breast cancer." (PMID 37004014, 2023).